PTPN7 (protein tyrosine phosphatase non-receptor type 7)
Description:
Protein phosphatase that acts preferentially on tyrosine-phosphorylated MAPK1. Plays a role in the regulation of T and B-lymphocyte development and signal transduction.
Synonyms: HEPTP; LC-PTP; BPTP-4; LPTP; PTPNI
Tractability: Small molecule: a structure with a bound ligand is known; a high-quality ligand is known; it belongs to a druggable protein family. PROTAC: ubiquitination databases record sites on it; its protein half-life has been measured; a small molecule that binds it is known.
Target class: Tyrosine protein phosphatase; Enzyme; Phosphatase; Protein Phosphatase
Gene: Protein-coding gene on chromosome 1 (202,147,012 to 202,161,588, reverse strand). Ensembl gene ENSG00000143851.
Subcellular location: Cytoplasm; Cytoplasm, cytoskeleton
Subcellular location (Human Protein Atlas): Cytosol; Microtubules; Mitotic spindle
Pathways (Reactome):
Immune System: Interleukin-37 signaling
Signal Transduction: Negative regulation of MAPK pathway
Gene Ontology:
Molecular function: protein binding; non-membrane spanning protein tyrosine phosphatase activity; protein tyrosine phosphatase activity
Biological process: MAPK cascade; protein dephosphorylation; signal transduction
Cellular component: cytoplasm; cytoplasmic side of plasma membrane; cytosol; nucleoplasm; cytoskeleton
Genetic constraint (gnomAD): Loss-of-function variants: 33 observed, 50.91 expected, observed/expected ratio (o/e) 0.65, 90% interval 0.49 to 0.87. The upper end of that interval is the gene's LOEUF score, 0.87, which puts it in group 3 of 6, group 1 being the genes least tolerant of losing a copy. Missense variants: 412 observed, 493.92 expected, observed/expected ratio (o/e) 0.83, 90% interval 0.77 to 0.9. Synonymous variants: 185 observed, 193.58 expected, observed/expected ratio (o/e) 0.96, 90% interval 0.85 to 1.08.
Homologues: Orthologues: chimpanzee PTPN7 (99% identical), macaque PTPN7 (98% identical), dog PTPN7 (92% identical), mouse Ptpn7 (92% identical), rat Ptpn7 (91% identical), guinea pig PTPN7 (91% identical), pig PTPN7 (86% identical). Paralogues in human: PTPRR (54% identical), PTPN5 (50% identical), PTPRB (36% identical), PTPRJ (33% identical), PTPRT (33% identical), PTPRF (32% identical), PTPRK (32% identical), PTPRS (32% identical), PTPRO (32% identical), PTPRG (32% identical), PTPRD (31% identical), PTPRU (31% identical), and 23 more.
Diseases named in the same sentence as PTPN7 in open-access papers:
PTPN7 is named in the same sentence as 25 diseases in open-access papers, as found by Europe PMC text mining. Sharing a sentence is not in itself a finding about the gene and the disease. The quoted sentences say what the papers report.
breast carcinoma (7 papers, 2013 to 2025). "PTPN7 is involved in immune infiltration and is strongly correlated with immunothermal tumors in breast cancer." (PMID 40703522, 2025). "They uncovered that the expression of PTPN20, PTPN7, and several other PTPs were significantly augmented in breast cancer tissues compared to normal tissues and identified a strong correlation between PTPN7 expression and immune infiltration." (PMID 37359510, 2023). "PTPN7, a member of the non‐receptor protein tyrosine phosphatase (PTPN) family primarily involved in tyrosine phosphorylation, has been identified as being associated with immune‐related tumours in various cancers, including breast cancer." (PMID 40360443, 2025).
glioma (2 papers, 2023 to 2025). A benign or malignant brain and spinal cord tumor that arises from glial cells (astrocytes, oligodendrocytes, ependymal cells). "In digestive tract cancer, bladder cancer and glioma, PTPN7 can serves as a predictive tumor biomarker." (PMID 40703522, 2025).
leukemia (2 papers, 2020 to 2022). A malignant (clonal) hematologic disorder, involving hematopoietic stem cells and characterized by the presence of primitive or atypical myeloid or lymphoid cells in the bone marrow and the blood. "PTPN7 is a protein tyrosine phosphatase known to dephosphorylate MAPKs in hematopoietic cells, deregulated via amplifications in leukemias but deletions in lymphomas." (PMID 32679859, 2020).
lymphoma (2 papers, 2020 to 2025). A malignant (clonal) proliferation of B- lymphocytes or T- lymphocytes which involves the lymph nodes, bone marrow and/or extranodal sites. "Through SMR analysis, we identified WARS2 and PTPN7 as key regulators of CD28−CD25++CD8br%CD8br immune cells and various lymphomas." (PMID 40360443, 2025).
melanoma (2 papers, 2022 to 2024). A malignant, usually aggressive tumor composed of atypical, neoplastic melanocytes. "This approach allowed us to prioritize PTPN7, a prognostic predictor of melanoma, as the gene target of miR-592 for mechanistic characterization." (PMID 36302748, 2022). "Further, we show the prognostic values of miR-592 and PTPN7 in melanoma." (PMID 36302748, 2022). "Uptaken miR-592 inhibits the expression of its target gene protein tyrosine phosphatase non-receptor type 7 (PTPN7), leading to the activation of the MAPK/ERK signaling pathway and, ultimately, to the promotion of melanoma cell metastatic ability." (PMID 39199632, 2024). "Via the EV-miR-592/PTPN7/MAPK axis, melanoma-CSCs can transfer their metastatic ability to the low-metastatic non-CSC melanoma parental cells." (PMID 36302748, 2022). "PTPN7 overexpression in miR-592-OE-MPCs successfully prevented the miR-592-induced enhancement of MAPK/ERK activation (Uncropped WB), we observed the same results in A375, another human malignant melanoma cell line." (PMID 36302748, 2022). "Thus, via the extracellular vesicle miR-592/PTPN7/MAPK axis, melanoma stem cells (MSCs) can transfer their metastatic ability to the low-metastatic non-CSC melanoma cells." (PMID 36302748, 2022). "Thus, via the EV-miR-592/PTPN7/MAPK axis, melanoma-CSCs can transfer their “metastatic ability” to the low-metastatic non-CSC melanoma cells." (PMID 36302748, 2022). "Thus, via the extracellular vesicle miR-592/PTPN7/MAPK axis, melanoma-CSCs can transfer their metastatic ability to the low-metastatic non-CSC melanoma cells." (PMID 36302748, 2022).
acute myelogenous leukemia (1 paper, 2023). "PTPN7/HePTP is often upregulated in myelodysplastic syndrome, T cell acute lymphoblastic leukemia, and acute myelogenous leukemia." (PMID 37240404, 2023).
anxiety disorder (1 paper, 2023). A category of psychiatric disorders which are characterized by anxious feelings or fear often accompanied by physical symptoms associated with anxiety. "Nevertheless, PTPN7 may be a promising candidate connecting ELA, the immune response, and MAPK signaling as a potential regulator of anxiety disorders." (PMID 37181876, 2023).
colon adenocarcinoma (1 paper, 2020). "In our study, PTPN5 and PTPN7 were found to be correlated with prognosis of colon adenocarcinoma patients, while PTPN6 and PTPN13 were statistically associated with the prognosis of STAD." (PMID 32536826, 2020).
colorectal cancer (1 paper, 2020). A primary or metastatic malignant neoplasm that affects the colon or rectum. "For colorectal cancer (CRC), PTPN2, PTPN21 and PTPN22 levels were correlated with incidence; expression of PTPN5, PTPN12, and PTPN14 was correlated with TNM stage and N stage; high PTPN5 or PTPN7 expression was associated with increased hazards of death." (PMID 32536826, 2020).
esophageal cancer (1 paper, 2012). A primary or metastatic malignant neoplasm involving the esophagus. "This expression pattern is similar to that of PTPN7 and PTPN13, which were reported to be at a global loss in a wide range of cancers including breast, kidney, and esophageal cancers." (PMID 22394684, 2012).
lymphoproliferative disorders (1 paper, 2022). "PTPN7 is amplified in myeloid malignancies and deleted in lymphoproliferative disorders." (PMID 36556168, 2022).
neuroblastoma (1 paper, 2021). Neuroblastoma (NB) is the most common solid, extracranial childhood tumor. "Interestingly, a distinct pattern of PTPRR, PTPN5, and PTPN7 mRNA expression was observed in human neuroblastoma cell lines upon retinoic acid differentiation, with down-regulation of PTPN5 and up-regulation of PTPN7 and, to a lesser extent, PTPRR." (PMID 34957126, 2021).
non-small cell lung carcinoma (1 paper, 2022). A group of at least three distinct histological types of lung cancer, including non-small cell squamous cell carcinoma, adenocarcinoma, and large cell carcinoma. "Interestingly, we observe that PTPN7 is kind of PD-1’s substitute in the non-small cell lung cancer which performs almost equal contribution as PD-1." (PMID 36226189, 2022).
triple-negative breast carcinoma (1 paper, 2022). An invasive breast carcinoma which is negative for expression of estrogen receptor (ER), progesterone receptor (PR), and human epidermal growth factor receptor 2 (HER2). "For example, in triple negative breast cancer, PTPN7 cannot separate patients into groups with significant survival difference." (PMID 35610556, 2022).
tumor (6 papers, 2021 to 2025). "Another gene implicated in apoptosis resistance is PTPN7, as the knockout of this gene resulted in three times increase in apoptosis, while overexpression resulted in tumor morphological features in myeloid cells." (PMID 34204115, 2021). "The immune interaction and mechanism between PTPN7 and infiltration derived by immune cells in pan-cancer was analyzed, PTPN7 was negatively correlated with tumor purity but positively correlated with multiple immune cells infiltration in most cancer types." (PMID 36226189, 2022). "In the term of PTPN7 expression, there was a substantial difference between BrCa and paracancerous tissues which revealed the PTPN7 expression was higher in tumor tissues." (PMID 36226189, 2022). "The intracellular content level of PTPNs in BrCa found in public databases was inconsistent, but PTPN7 was overexpressed in tumor tissues compared to paired para-tumor tissues in the current cohort." (PMID 36226189, 2022). "We discovered that PTPN7 was adversely connected with tumor purity in BrCa tumor types, but positively correlated with numerous immune cell infiltration." (PMID 36226189, 2022). "Collectively, these findings uncover that PTPN7 may play a vital role in the tumor immunity in the pan-cancer." (PMID 36226189, 2022). "The correlation between PTPN7 and these immune characteristics suggests that PTPN7 plays an important role in regulating the tumor immune microenvironment that indicates PTPN7 would be a promising biomarker for the immunotherapy sensitivity or the thermal and cold pointer vice versa." (PMID 36226189, 2022). "High level mRNA expressions of PTPN7 and PTPN22 were significantly negatively correlated with tumor purity." (PMID 36226189, 2022). "We analyzed the expression levels of PTPNs in the TCGA database and discovered that PTPN1, PTPN6, PTPN7, PTPN18, PTPN20, and PTPN22 were significantly upregulated in tumor samples, while PTPN4, PTPN5, PTPN10, PTPN11, PTPN13, PTPN14, and PTPN21 were downregulated in tumor samples." (PMID 36226189, 2022). "In our study, we confirmed that PTPN7 expression in normal tissue is lower than in PAAD tissue, However, the correlation between this expression and tumor stage was not obvious in PAAD patients." (PMID 35154122, 2022).
cancer (5 papers, 2012 to 2025). A tumor composed of atypical neoplastic, often pleomorphic cells that invade other tissues. "Subsequently, we analyzed the expression of PTPN7 and its immunological correlation in pan-cancer tissues." (PMID 36226189, 2022). "To reveal the relationship between PTPNs and BrCa and pan-cancer, we conducted a demonstration of PTPN7 as a biomarker in predicting the response of immunotherapy to diverse tumors that provide immuno-hot signals." (PMID 36226189, 2022). "PTPN7 has been associated with CTLA-4 and PD-L1 expression in almost all cancer types." (PMID 37685980, 2023). "Given the pan-cancer positive correlation between PTPN7 and immuno-factors, we speculated that PTPN7 could be an innovative biomarker to forecast the consequence to immunotherapy." (PMID 36226189, 2022). "Overall, PTPN7 can be a novel biomarker to predict the response to immunotherapy in cancer." (PMID 36226189, 2022). "Moreover, the immune correlations of PTPN7 in BrCa and pan-cancer were further investigated based on the TCGA cohort and were testified using the in-house and the Gene Expression Omnibus (GEO) cohorts." (PMID 36226189, 2022). "The phenomena of PTPN7 which overexpressed during the pan cancer genesis is prospective for in-depth research that may be helpful to recognized PTPN7 as a novel pan cancer biomarker." (PMID 36226189, 2022). "The CNV percentage in pan-cancer indicated that heterozygous amplification in cancers were widely found in genes PTPN1, PTPN7, PTPN12 and PTPN14 in most cancers, while heterozygous deletions were widely found in genes PTPN13, PTPN20, PTPN22 and PTPN23." (PMID 37884566, 2023). "The pan-cancer analysis revealed that PTPN7 was related to PD-L1 and CTLA-4 expression in almost all cancer types." (PMID 36226189, 2022). "Further studies suggested that PTPN7 significantly activated apoptosis, and EMT pathway in pan-cancer, PTPN2 significantly activated apoptosis and cell cycle pathway in pan-cancer, while PTPN21 significantly inhibited apoptosis and cell cycle pathway in pan-cancer." (PMID 37884566, 2023). "Moreover, the pan-cancer analysis of PTPN7 was also conducted, which revealed that PTPN7 might be a novel predictive biomarker for immunotherapy." (PMID 36226189, 2022).
neurodegenerative disease (1 paper, 2023). A disorder of the central nervous system characterized by gradual and progressive loss of neural tissue and neurologic function. "PTPN3 is a potential immune checkpoint inhibitor target that may mediate T cells, while PTPN5 and PTPN7 can specifically inactivate MAPKs, so the developed inhibitors may have therapeutic potential for treating neurodegenerative diseases in AML patients." (PMID 37884566, 2023).
PTPN7 also shares sentences with these, for which no sentence is quoted: bladder cancer (1 paper); coronary heart disease (1); developmental delay (1); hepatocellular carcinoma (1); lung carcinoma (1); myelodysplastic syndrome (1); stomach adenocarcinoma (1); type B thymomas (1).